NLRP3 (NLR family pyrin domain containing 3)
Diseases named in the same sentence as NLRP3 in open-access papers (continued):
Sharing a sentence is not in itself a finding about the gene and the disease.
tumor (continued). "Nigericin and combination of LPS with Nigericin (LPS/Nigericin) increased NLRP3 protein expression in all tumor cell lines as compared to untreated tumor cells and in Nigericin and LPS/Nigericin treated fibroblasts as compared to untreated fibroblasts." (PMID 33613529, 2020). "NLRP3 inflammasome activation in tumor cells can endorse a chronic inflammatory TME that encourages malignant transformation and extinguishes the local immunity provided by NK or T cells." (PMID 33613533, 2020). "Not only does the cytokine dampen immune surveillance, but it also blunts the anti-tumor therapeutic effect of chemotherapeutic agents via drug-induced NLRP3 activation in MDSC as well." (PMID 33613533, 2020). "In cancer, analysis of copy number alterations in tumor samples has shown NLRP3 with a high frequency of copy gains, thus acting more as an oncogene." (PMID 32733479, 2020). "The NLRP3 inflammasome is involved in tumor development, although the precise role of the NLRP3 inflammasome is unclear since the cytokines it produces suppress some cancers, while they facilitate tumorigenesis of other cancers." (PMID 31923221, 2020). "NLRP3 triggers innate immunity by activating caspase-1, then cleaves the inflammatory molecule IL-1β and IL-18, which induces inflammation and eliminate tumor cells." (PMID 33603669, 2020). "NLRP3 inflammasome in the tumor microenvironment inhibits antitumor T cell immunity by facilitating the migration of myeloid-derived suppressor cells (MDSCs) to the site of the tumor." (PMID 32974137, 2020). "A high cholesterol diet is also responsible for macrophage production of IL-1β, through NLRP3 activation, and tumor growth in azoxymethane-induced colon cancer." (PMID 32635472, 2020). "In contrast, in tumor cell lines where NLRP3 activation and, IL-1β and IL-18 secretion are high, although Nigericin triggers initial tumor cell death, cells recover and tumors remain active." (PMID 33613529, 2020). "In manipulating the expression of inflammasome, researchers have found that NLRP3 serves as a deterministic player in conducting tumor fate decisions." (PMID 33613533, 2020). "This was mirrored in human pancreatic ductal adenocarcinoma, where tumour infiltrating monocytes expressed significantly more NLRP3 protein than circulating monocytes." (PMID 32883606, 2020). "The genetic and pharmacological inhibition of NLRP3 inhibited the tumor infiltration of PMN-MDSCs and significantly enhanced the efficacy of Anti-PD-1 immunotherapy." (PMID 33344447, 2020). "The P2XR mediates host–tumor cell interactions and triggers NLRP3 activation via cytosolic Ca2+ influx and K+ efflux, thereby shaping the TME and tumor fate." (PMID 33613533, 2020). "In the primary lesion of cancer cells, NLRP3 drives the production of pro-IL-1β, DC maturation, and the secretion of IL-1β to support the differentiation of tumor-specific CD8+ T cells." (PMID 33613533, 2020). "NLRP3 staining was negligible or faint in tumor stroma and stronger in scattered cells throughout the tissue." (PMID 31923221, 2020). "Collectively, LncRNA ADAMTS9-AS2 acted as a tumor suppressor and enhanced cisplatin sensitivity in GC cells by activating NLRP3 mediated pyroptotic cell death through sponging miR-223-3p." (PMID 32516127, 2020). "The effect of NLRP3 stimulation and inhibition on tumor cell viability was also confirmed by activating NLRP3 by LPS/ATP and suppressing NLRP3 using glibenclamide." (PMID 33613529, 2020). "Collectively, these studies suggest classical tumor-promotive effects of NLRP3 and AIM2 in epithelial cells." (PMID 32778128, 2020). "On the other hand, some chemotherapy treatment induced NLRP3 activation has been described as beneficial for battling tumours." (PMID 32883606, 2020). "NLRP3 expression in tumor-infiltrating macrophages also correlated with survival, lymph node invasion, and metastasis of mammary carcinoma patients." (PMID 31231372, 2019).
tumor (continued). "Recent studies suggest that most experimental and clinical studies support NLRP3 inflammasome to promote tumor development." (PMID 31312615, 2019). "We next sought to investigate the functional role of CAF-derived NLRP3/IL-1β pathway in tumour growth in vivo." (PMID 31558756, 2019). "Studies shown that the NLRP3 inflammasome participates in the innate immune response to CC and its expression is widely present in tumor cells." (PMID 31501419, 2019). "These suggest that ATP accumulated in tumor microenvironment would activate NLRP3 inflammasome resulting in the increased secretion of IL-1β from immune cells." (PMID 31439870, 2019). "Nrf2 promoted tumor progression by activation of anti-oxidant enzymes and NLRP3 inflammasome complexes." (PMID 31442293, 2019). "We found that tumours co-injected with CAFs in which Nlrp3 or Il1b were depleted had significantly downregulated expression of pro-inflammatory genes related to immune cell recruitment." (PMID 31558756, 2019). "Based on above results, we considered that the NLRP3 was tumor suppressor gene in ccRCC and the NLRP3 inflammasome is an important functional effector of LXRα in ccRCC cells for the first time." (PMID 30770793, 2019). "The results would provide a novel anti-cancer strategy using NLRP3 inflammasome inhibitors, such as celastrol to modulate the myeloid cells in tumor microenvironment and tumor metastatic potential by reducing the IL-1β level at tumor sites." (PMID 31439870, 2019). "In WT mice, B(a)p plus LPS exposure significantly increased tumor incidence, mean tumor count and tumor size of visible tumors of lungs compared with B(a)p treatment alone, and NLRP3 deletion inhibited lung tumorigenesis induced by B(a)p or B(a)p plus LPS." (PMID 30696442, 2019). "By comparing BC tumor formation in caspase-1 knock-out (KO) mice, and NLRP3 KO C57BL/6 mice with the wild-type mice, it was proven that the NLRP3 inflammasome is the most common type of inflammasome formed in breast malignant tissue." (PMID 31661891, 2019). "IL-1β, one of the most abundant pro-inflammatory cytokines of the tumour microenvironment, and NLRP3-inflammasome activation have been involved in tumourigenesis and progression of PCa." (PMID 31480312, 2019). "Remarkably, NLRP3 expression by TAMs in PDAC murine models has been recently shown to exert tumor-promoting functions and its ablation significantly prolonged mice survival." (PMID 30760333, 2019). "In NLRP3−/− and IL-1β−/− mice models, treatment with 5-FU shows a long term tumor growth regression." (PMID 31217433, 2019). "In summary, our study reveals tumour-promoting functions of CAFs in sensing tumour-induced tissue damage, leading to activation of the NLRP3 inflammasome pathway and secretion of IL-1β, which promotes tumour progression and lung metastasis." (PMID 31558756, 2019). "The inhibition of NLRP3 inflammasome by celastrol in macrophages results in the suppression of tumor metastatic potential." (PMID 31439870, 2019). "To investigate this further, we injected anti-CTLA-4 or anti-PD-1 mAb in EG7 tumor-bearing Casp1/11−/− or Nlrp3−/− mice." (PMID 31085177, 2019). "Alternatively, carcinoma-derived proteins were found to activate the NLRP3 inflammasome, which resulted in FasL-mediated NK cell cytotoxicity against metastatic tumor cells and effective tumor suppression after IL-18 activation of NK cells." (PMID 32010140, 2019). "To determine if NLRP3 inflammasome plays a vital role in inflammation-driven lung tumorigenesis, we compared the tumor incidence, multiplicity and the size of visible tumors on the surface of the lung in WT mice and NLRP3−/− mice." (PMID 30696442, 2019). "The IHC staining with tumor tissues showed the strong expression of NLRP3 in the saline group and soluplus group, while r-As4S4 treatment decreased the NLRP3 expression slightly." (PMID 31106156, 2019).
tumor (continued). "ATP abundant in tumor microenvironment stimulates the NLRP3 inflammasome in macrophages, releasing mature IL-1β to the tumor microenvironment to enhance the metastatic potential of cancer cells." (PMID 31439870, 2019). "Seeking to characterise the mechanism by which CAF-derived NLRP3 affects tumour growth, we analysed parameters that were previously shown to be affected by CAFs, including fibrosis, immune cell recruitment, and angiogenesis." (PMID 31558756, 2019). "The results would provide a novel anti-cancer strategy to modulate tumor microenvironment by suppressing NLRP3 inflammasome and consequently reducing IL-1β production." (PMID 31439870, 2019). "Although NLRP3 expression in tissue-infiltrated macrophages has been associated with higher susceptibility to CRC and its aggressiveness, its role in tumor cells is, at a first glance, controversial." (PMID 30837326, 2019). "The indecisive role of the NLRP3 inflammasome in cancer is yet another reminder that complexity and context-dependent functions are hallmarks of the tumour microenvironment, and should therefore be carefully considered when designing therapeutic strategies." (PMID 31558756, 2019). "Our results demonstrate that suppression of ATP-induced NLRP3 inflammasome activation and IL-1β secretion in tumor microenvironment, contributes to decreasing metastatic potential of cancer cells." (PMID 31439870, 2019). "NLRP3 is constitutively activated and leads to sustained local and systemic inflammation mediated by IL-1β in the tumor." (PMID 31106156, 2019). "Our results propose the NLRP3 inflammasome as a new anti-cancer target of celastrol for the regulation of myeloid cell activation in tumor microenvironment." (PMID 31439870, 2019). "To that end, we performed orthotopic co-injections of fibroblasts and tumour cells into Nlrp3−/− mice." (PMID 31558756, 2019). "NLRP3 expression has also been found in macrophages infiltrated in CRC tissues, and the inhibition of NLRP3 pathway leads to decreased tumor cell migration, invasion and metastatic potential." (PMID 30837326, 2019). "2-DG inoculation also attenuated the increased expression levels of NLRP3, caspase-1 p45, and IL-1β p31 in tumor-metastasized lungs." (PMID 30586442, 2018). "The precise clinical function of NLRP3 in the role of the initiation and promotion of differing neoplasms also highlights the therapeutic potential of inflammasomes, and as prognostic markers." (PMID 30447690, 2018). "HNSCC can induce the production of active IL-1β through NLRP3 inflammasome pathways, and inhibition of the NLRP3 inflammasome pathway was suggested to be a promising approach for decreasing tumour cell invasion and survival." (PMID 30447690, 2018). "Obvious expression of NLRP3 and IL-1β was found in the paraffin-embedded OSCC tissues, and the NLRP3 expression levels were correlated with the tumor size, lymphonode metastatic status and IL-1β expression." (PMID 29716544, 2018). "Activation of NLRP3 inflammasome has also been shown to promote inflammation-induced tumor growth and metastasis in head and neck cancer and oral squamous carcinoma." (PMID 30631327, 2018). "The NLRP3 expression in OSCC tissues was positively correlated with tumor size, lymphonode metastasis status and IL-1β expression (product of the activated NLRP3 inflammsome)." (PMID 29716544, 2018). "NLRP3 inflammasome has been recognized to be important for tumor control by directly activating pyroptotic cell death or secreting death-inducing cytokines." (PMID 30319645, 2018). "NLRP3 signaling in macrophages drives the differentiation of CD4+ T cells into tumor-promoting Th2, Th17, and T-regulatory cell types, while suppressing Th1 cell polarization and cytotoxic CD8+ T cell activation." (PMID 30631327, 2018). "Together, these results indicate that XLOC_000647 functions as a novel tumor suppressor of lncRNA and acts as an important regulator of NLRP3, inhibiting cell proliferation, invasion, and EMT in PC." (PMID 29386037, 2018).
tumor (continued). "Since the activation of NLRP3 drives pyroptotic and immunogenic cell death, its direct activation within the tumor has been described as an efficient mechanism to mediate a potent and persistent antitumor immunity." (PMID 30619282, 2018). "It is interesting to note that the inflammasome component NLRP3 also impairs the impact of anti-tumor vaccine." (PMID 30631327, 2018). "The increased tumor incidence found in Nlrp3−/− and Casp1−/− mice correlated with an important local reduction of Il-18 levels and an increased colonic infiltration of macrophages." (PMID 29868004, 2018). "The tumor-suppressive effect of NLRP3 inflammasome on liver CRC metastasis is highly dependent on IL-18, which promotes the maturation of hepatic NK cells and primes FasL-mediated cytotoxicity." (PMID 30319645, 2018). "In experimental studies, NLRP3 and thereby IL-1β expression levels were correlated with the tumor size and the metastatic status of the sentinel lymph node." (PMID 30042333, 2018). "There is increasing attention directed toward identifying the role of the NLRP3 inflammasome in differing tumor types, and the activation of inflammasomes in tumor formation, development and invasion remains controversial and conflicting." (PMID 30447690, 2018). "MCC950 inhibited NLRP3 activation and caspase-1 dependent IL-1β processing, and hence improved anti-tumor immune response in head and neck squamous cell carcinoma." (PMID 30631327, 2018). "NLRP3 has also been described as important for angiogenesis, in tumour models and in matrigel plugs." (PMID 30360489, 2018). "In agreement, in a mouse breast cancer model inhibition of NLRP3 effectively reduced the tumor-resident population of MDCS and TAM." (PMID 30042333, 2018). "Our data demonstrated the overexpression of NLRP3 in OSCC cells promoted OSCC tumor growth and metastasis." (PMID 29716544, 2018). "In a human oral squamous cell carcinoma (OSCC) model NLRP3 expression levels correlated with tumor size, lymph node metastatic status and IL-1β expression." (PMID 30042333, 2018). "With the carcinogen-induced OSCC model, we found less and later tumor incidence in Nlrp3−/− and Caspase1−/− mice than wild-type mice." (PMID 28637493, 2017). "Up-regulation of IL-18 can activate NLRP3, promote proliferation, inhibit apoptosis, and inhibit the anti-tumor effect of dexamethasone." (PMID 29312552, 2017). "Ki-67 is one of the most commonly used proliferation markers of tumor cells, thus we examined its expression and evaluated its relation with NLRP3." (PMID 28637493, 2017). "Then we investigated the potential roles of NLRP3 inflammasome in tumor carcinogenesis and self-renewal capacity of cancer cells in SCCHN cell lines and transgenic mouse SCCHN model." (PMID 28865486, 2017). "This work indicates that LMP1-mediated glycolysis regulates IL-1β, IL-6 and GM-CSF production through the NLRP3 inflammasome, COX-2 and P-p65 signaling pathways to enhance tumor-associated MDSC expansion, which leads to tumor immunosuppression in NPC." (PMID 28732079, 2017). "And 5-FU significantly suppressed tumor growth in all three groups of mice, with greater inhibition in Nlrp3−/− and Caspase1−/− mice than in wild-type mice." (PMID 28637493, 2017). "We compared the various tumor properties and prognosis of each patient and found correlation(s) with degrees of NLRP3 inflammasome overexpression." (PMID 28430665, 2017). "We established the OSCC xenograft mouse model with WSU-HN6 and CAL27 cells and found that 5-FU treatment significantly limited OSCC growth and obviously increased the expression of NLRP3 and IL-1β in tumor cells." (PMID 28637493, 2017). "Studies have found that NLRP3 inflammasome plays an important role in tumor development and chemotherapy resistance." (PMID 29312552, 2017).
tumor (continued). "Cell sorting and transcriptome analysis of TAMs from both tumor entities revealed reduced expression of the inflammasome component Nlrp3 in S1PR1-deficient TAMs, which correlated with decreased IL-1β levels in tumor tissue." (PMID 28804221, 2017). "Increased glycolysis promotes tumor-associated MDSC expansion in the NPC microenvironment by triggering the activation of p65 and the NLRP3 inflammasome signaling pathway, which leads to the production of IL-1β, IL6 and GM-CSF by malignant NPC cells." (PMID 28732079, 2017). "NLRP3 inflammasome is a key player in the progression of cancers, but its role in tumorigenesis and tumor environment are complex." (PMID 28865486, 2017). "Here the authors show that antigen-induced perforin release from CD8 T cells into antigen-presenting cells can activate NLRP3 inflammasome to constitute a positive feedback loop to promote anti-tumour immunity and allo-responses." (PMID 28537251, 2017). "A spontaneous de novo SCCHN mice model for tumorigenesis studies was applied to further determine the potential role of NLRP3 inflammasome in tumor initiation effect." (PMID 28865486, 2017). "The authors further demonstrated that NLRP3-inflammasome activation in bone marrow-derived cells was critical for the tumor suppression." (PMID 27786298, 2016). "In conclusion, our data imply lung tumor lesions are populated by macrophages which pro-tumor activity is regulated by the activation of the NLRP3 inflammasome that leads to the release of IL-1α and IL-1β in a caspase-11/caspase-1-dependent manner." (PMID 27528423, 2016). "Here, we demonstrate for the first time that NLRP3 and its inflammasome-associated proteins, ASC, IL-1β, and CASP1, are highly expressed in OSCC tumor tissues, as examined by immunohistochemistry (IHC), Western blot and RT-qPCR analyses." (PMID 27367024, 2016). "Taken together these data imply that lung tumor lesions are populated by macrophages which pro-tumor activity is regulated by the activation of the NLRP3 inflammasome that leads to the release of IL-1α and IL-1β." (PMID 27528423, 2016). "The authors suggested that the expression of NLRP3 in the tumor microenvironment diminishes DC vaccine-induced anti-tumor immunity." (PMID 27786298, 2016). "Our results showed that tumor growth and metastasis were also decreased in NLRP3 KO mice after injection of PyT8 tumor cells." (PMID 27786298, 2016). "In the EO771 tumor model, WT and NLRP3 KO female mice were injected orthotopically with tumor cells." (PMID 27786298, 2016). "We found that the amount of mature or processed IL-1β and caspase-1 proteins in tumor tissues of caspase-1 KO and NLRP3 KO mice were significantly decreased, compared to that of WT mice." (PMID 27786298, 2016). "RT-qPCR analysis of 20 paired tumor and adjacent normal tissue samples revealed that the mRNA levels of ASC, along with IL-1β, CASP1, and NLRP3 in ASC-associated NLRP3 inflammasome were significantly elevated in OSCC tissues." (PMID 27367024, 2016). "Taken together these data imply that lung tumor lesions are populated by macrophages which pro-tumor activity is regulated by the activation of the NLRP3 inflammasome that leads to the release of IL-1α and IL-1β in a caspase-11/caspase-1-dependent manner." (PMID 27528423, 2016). "We next used immunohistochemical (IHC) staining to evaluate the protein expression levels of ASC, IL-1β, CASP1 and NLRP3 in tumor cells using a second cohort of OSCC biopsy samples (n=111)." (PMID 27367024, 2016). "Current view holds that NLRP3 interferes with tumor progression in virtue of its ability to modulate cytokine release and cell death (pyroptosis), and thus control inflammation." (PMID 27221966, 2016). "In recent years, the important role of NLRP3 inflammasome in carcinogenesis and tumor progression has been reported." (PMID 27652274, 2016).